INS (insulin)
Diseases named in the same sentence as INS in open-access papers (continued):
Sharing a sentence is not in itself a finding about the gene and the disease.
Obesity (continued). "Therefore, cognitive dysfunction related to HFD or obesity in otherwise healthy individuals may be due to decreased insulin signaling and development of BIR in the hippocampus." (PMID 31417349, 2019). "Obesity usually has a negative metabolic impact associated to an excessive and abnormal adipose tissue deposition and function, which affects several physiological processes such as glucose homeostasis and insulin sensitivity." (PMID 31877696, 2019). "Therefore sarcopenia (loss of skeletal muscle mass and/or muscle function) and age or obesity related skeletal muscle resistance to insulin may contribute to the metabolic dysregulation and the development of MetS." (PMID 30673715, 2019). "Insulin can influence the proteomic profile of EVs but whether RNA, lipoproteins and proteins from EVs change synergistically during hyperglycaemia or in response to insulin or obesity remains unknown." (PMID 31690986, 2019). "Considering that attendance was similar, we can only speculate on the reasons for these observed differences, but they may be related to insulin resistance, intramuscular fat infiltration, and/or inflammation which are disturbed metabolic features frequently related to obesity." (PMID 30906596, 2019). "Therefore, it is unclear whether BCM and islet number in WT mice fed HSTD for 22 weeks are increased, compared with those in mice fed NC due to excess supplementation of glucose, the final product of starch, or to obesity and decrease in insulin sensitivity." (PMID 31083314, 2019). "However, several rodent studies have shown that suckling pups of mothers who were fed high-fat diets to induce obesity were programmed to develop insulin and leptin resistance and subsequent metabolic disorder, predisposing the offspring to develop obesity later in life." (PMID 31141526, 2019). "Thus, the same approach might be useful for administering novel drugs that reverse or bypass the blockage point of insulin signaling as an obesity treatment, once the blockage mechanism and the responsible molecules have been fully elucidated." (PMID 30875909, 2019). "Among the factors that link obesity to carcinogenesis are the activation of the insulin/IGF-1 pathway, increased concentrations of pro-inflammatory cytokines (TNF-α, IL-1 and IL-6) and their influence on adipocytokines, and dyslipidemia, which is often associated only to obesity." (PMID 31703601, 2019). "We took a reductionist approach and assessed three stressors that are elevated in obesity (glucose, insulin, and palmitic acid) that may be mediating this effect and determined their effects on macrophage CEC alone and in combination at physiologically relevant concentrations." (PMID 30411491, 2019). "Additionally, the administration of vaspin led to significantly smaller adipocytes, reduced expression of IL-6, and increased expression of GLUT4, suggesting that vaspin could potentially be used to increase insulin sensitivity and inhibit obesity." (PMID 30909620, 2019). "As discussed in the context of obesity, low mitochondrial respiration may thus be a consequence of lost insulin sensitivity in uraemia rather than a cause." (PMID 31195596, 2019). "While a complete understanding of obesity and its metabolic consequences has yet to be achieved, increased oxidative stress in skeletal muscle has recently been proposed as a unifying mechanism promoting mitochondrial dysfunction, lipid accumulation, and insulin resistance." (PMID 31600210, 2019). "With this background, and to further validate AAV-mediated hepatic IRA expression as a potential gene therapy tool for decreasing hyperglycemia in insulin-resistant states, we hypothesized that this gene therapy approach could also work in a mouse model of diet-induced obesity." (PMID 30642871, 2019). "Interestingly, there are elevated circulating and tissue levels of both insulin growth factor and insulin in obesity, suggesting that a combination of elevated growth factors may increase cancer risk." (PMID 31311976, 2019).
Obesity (continued). "Clearly, it could be hypothesized that specific pharmacological inhibitors against particular RNA-RBPs would restore normal insulin signaling, glucose and lipid metabolism, and ameliorate inflammation and fibrosis of metabolic tissues, such as is observed in obesity-induced steatohepatitis." (PMID 31482095, 2019). "We were not able to test association of MRS with other obesity-associated outcomes, such as cancer, which may be related to unchecked weight gain and anabolic effects of insulin." (PMID 31560688, 2019). "It is important to consider that a detrimental role of IL-6 exists and that obesity particularly increases IL-6 levels both in humans and mice due to macrophage secretion in the adipose tissue, promoting a low-grade systemic inflammation that can impair insulin signaling and glucose metabolism." (PMID 30875990, 2019). "Differential methylation in the circulation may predict the development of future T2D beyond traditional risk factors such as age and obesity, but it may also be part of the biological mechanism that links age and/or obesity to glucose, insulin metabolism and/or T2D." (PMID 31197173, 2019). "Taken together, these data lead us to state that despite skeletal muscle is considered to play an important role in the development of metabolic syndrome, this tissue would not be involved in the ROS‐drive obesity and insulin development induced by TP53INP1 deficiency." (PMID 31124296, 2019). "Therefore, insulin-signaling pathways seem to have an impact on obesity pathogenesis, although they are not the only cause, allowing the rationale for other nutritional approaches different from LCD." (PMID 31035514, 2019). "Ritchie and Connell concluded that obesity and the adiposity of internal organs were key factors in the development of tissue resistance to insulin because an increase in the content of visceral fatty tissue contributed to dyslipidaemia, the enhancement of gluconeogenesis, and insulin resistance." (PMID 31652553, 2019). "Theoretical formulations implicating dysmetabolic consequences of high carbohydrate diets on insulin-adipocyte physiology have resulted in increasing interest in the actively debated hypothesis that obesity and its co-morbidities can be restrained by reducing dietary carbohydrates." (PMID 31726791, 2019). "Our data suggest that higher energy and carbohydrate (starch and sugar) intakes of the ‘refined and processed’ pattern may drive hyper-insulin secretion and increased adiposity, leading to hyper-leptinaemia, as reported in previous studies describing the pathogenesis of obesity." (PMID 31323812, 2019). "Moreover, chlorpyrifos-altered microbiota could affect the occurrence of obesity and impaired insulin sensitivity." (PMID 30744700, 2019). "Thus, these genes might provide a novel characteristic to protect against the development of obesity and improve insulin sensitivity during adipogenesis." (PMID 31547433, 2019). "Moreover, vessel-dependent effects of insulin and insulin-like growth factor-1 on vascular tone and Akt activation may have implications in treating obesity-related vascular disease." (PMID 30295509, 2019). "Importantly, insulin and glucocorticoid signaling operate to cooperatively control the majority of feeding-mediated gene repression, and these signaling pathways are dysregulated in diet-induced obesity impacting dynamic hepatic gene expression." (PMID 30532187, 2018). "Since the association between mannose and insulin sensitivity (IS) in those with impaired glucose tolerance remains unknown, we aimed to investigate this association in individuals without severe obesity but with varying degrees of glucose tolerance." (PMID 30534205, 2018). "We may have expected a greater number of GWAS loci related specifically to insulin, however linear modeling does not fully capture the complex interactions between genes, insulin, obesity and risk of development of T2DM." (PMID 29986096, 2018).
Obesity (continued). "This suggests that although insulin, %TS, and RBC aggregation were independent predictors of circulating total T, the contributions of %TS and RBC aggregation to total T-associated dietary pattern were weaker and more likely to be influenced by obesity than insulin and total T." (PMID 30453566, 2018). "Moreover, blood asprosin might play a vital role in glucose homeostasis, insulin homeostasis, obesity, sex-related hormone metabolism, or inflammation in females with metabolic-related diseases." (PMID 30524197, 2018). "The present review will discuss the molecular and cellular features of beta cell heterogeneity at both the single-cell and islet level, explore how this influences islet function and insulin release and look into the alterations that may occur during obesity and T2DM." (PMID 29661799, 2018). "Therefore, to clearly evaluate the effects of obesity on cerebral health in the present study, we used a longterm HFD (20 weeks) to induce obesity in rats; then, we investigated the effects of obesity and subsequent treadmill exercise (TE) on brain insulin signaling and tau hyperphosphorylation." (PMID 29673239, 2018). "Obesity has also been shown to inhibit metabolic responses of BAT to ephedrine, insulin, or cold exposure; however, it is still unknown whether HFD-induced Ucp1 downregulation is related to causation, or whether it is a consequence of obesity." (PMID 29473916, 2018). "As resistin is an adipokine which has been shown to interfere with intracellular insulin signalling, and also stimulates monocyte and macrophage inflammatory cytokine production, this may contribute to the systemic low-grade inflammation observed in obesity." (PMID 30261617, 2018). "However, their function is reduced in insulin-responsive tissues in obesity and T2DM." (PMID 30477251, 2018). "TLR4 gene deletion in mice has a protective effect against adipose tissue inflammation and against the resistance to insulin action that is induced by the intake of a high fat diet, a fact that points towards the causal role played by TLR4 in metabolic changes driven by over-eating and obesity." (PMID 29601492, 2018). "Consistently, JNK1 but not JNK2 deficiency retained insulin sensitivity in diet-induced obesity." (PMID 30591653, 2018). "In obesity, inflammation can occur due to increased levels of chemokines (such as CCL2 and CXCL1) and inflammatory cytokines (such as tumor necrosis factor α (TNF-α) and interleukin-6 (IL-6)) secreted from accumulated fat in hepatocytes and adipocytes, causing insulin resistance." (PMID 29967759, 2018). "First, we could not control all the variables that could affect adipose gene expression apart from IR, but we tried to minimize the possible contribution of obesity on the signatures by including lean and obese subjects in both insulin sensitive and IR datasets." (PMID 29487289, 2018). "However, overeating-induced obesity results in impaired brain insulin signaling, which may lead to cognitive dysfunction and ultimately neurodegenerative disease." (PMID 29673239, 2018). "Since insulin has diverse functions in the body regulating carbohydrates and lipids by stimulating lipid synthesis from glucose and prevents lipid degradation or lipolysis, we evaluated the relationship between the ABCC8 C/T polymorphism with obesity, cholesterol, triglyceride and lipoproteins." (PMID 29751826, 2018). "Additionally, we hypothesized that HIIT would be more effective in improving markers of insulin signaling, MAPKs, mitochondrial biogenesis, and oxidative metabolism proteins in the skeletal muscle of insulin resistant individuals with obesity." (PMID 30429793, 2018). "Thus, obesity per se can act synergistically with maternal obesity to further increase circulating insulin and leptin levels, which may contribute to hypertension risk but not to additional loss of cardiac function." (PMID 29635288, 2018).
Obesity (continued). "However, there is also evidence that obesity leads to impaired cognitive functioning via reduced blood flow to the areas of the brain that control executive function or abnormalities in glucose and insulin regulation." (PMID 29802535, 2018). "Although obesity is typically a pathological state that results in the expansion of adipose tissue mass through both hypertrophy and hyperplasia, the failure of adipocytes to expand in response to excess energy intake can result in ectopic lipid deposition and insulin resistance." (PMID 29587377, 2018). "In women and young girls with this syndrome, obesity is one of the pathophysiological principles; consequently, increased level of insulin in these patients might stimulate the production of ovarian androgens and hence, would lead to ovulation disorder and infertility." (PMID 30514396, 2018). "However, nutritional excess enhances the secretion of insulin but blunts the response of organs to insulin and ultimately results in the clinical manifestation of T2DM, the most studied multifactorial metabolic disorder associated with obesity." (PMID 29484304, 2018). "In summary, we show that obesity changes the fat content of skeletal muscle and generally shows a negative impact upon blunt muscle injury on various cellular processes, among them fatty acid related metabolism, notch-, insulin-, sonic hedgehog-signaling, and apoptosis." (PMID 29441023, 2018). "Therefore, the increased lipogenesis as a consequence of elevated insulin levels may, at least in part, contribute to the development of obesity and impaired glucose homeostasis in Y1lox/lox/INS2cre/+ mice." (PMID 30177746, 2018). "Hence, it is possible that dyslipidemia and/or altered insulin signaling resulting from obesity may contribute to nerve pathology." (PMID 30446513, 2018). "In this regard, a striking amount of evidence has accumulated to suggest that changes to the epigenetic landscape in insulin-responsive tissues play an important role in the pathogenesis of obesity, insulin resistance, and T2D, and if reflected in blood, may represent potential biomarker candidates." (PMID 30564199, 2018). "In obesity, excess adipose tissue leads to hyperleptinemia and leptin resistance as well as increased production of pro-inflammatory cytokines resulting in decreases in whole body insulin sensitivity and disruption in appetite control and regulation of food intake." (PMID 30258366, 2018). "Therefore, it is not surprising that in our study obesity modified the association of insulin secretion with both IPA and inflammation." (PMID 29795366, 2018). "Elevated plasma free fatty acids (FFAs) associated with obesity or independent of obesity, i.e., consumption of a large amount of dietary fat, may impair the insulin signaling pathway leading to IR in the muscle and liver." (PMID 29614722, 2018). "Moreover, it should be determined whether overnutrition and obesity increases this basal insulin release." (PMID 29921789, 2018). "It is crucial to acknowledge a reduction in the amount of carbohydrate intake per se may not be optimal or a practical strategy for all women with PCOS, including those with normal BMI, certain non-insulin resistant phenotypes, and women with obesity in long-term." (PMID 30274344, 2018). "Thus, MLB may be used as a pharmaceutical agent that ameliorates hepatic insulin sensitivity and metabolic syndrome derived from aging and obesity." (PMID 30134566, 2018). "To that end we have demonstrated that tendon is an insulin target tissue, and that obesity/T2DM results in a substantial decrease in insulin sensitivity in HFD tendons at 48 weeks, suggesting that loss of IR signaling in HFD tendons may promote diabetic tendinopathy." (PMID 29907811, 2018).
Obesity (continued). "While some mechanisms of pathogenesis leading to comorbidity in an obesity or obesity-like state in mammals remain unknown, studies with mice and humans have revealed increased inflammation, aberrant cell signaling, decreased insulin sensitivity, and increased oxidative stress to be involved." (PMID 29141990, 2018). "Systemically, the insulin-lowering effects of metformin may contribute to its anti-cancer activity since insulin is a known mitogenic factor and hyperinsulinemia is one of the proposed mechanisms through which obesity promotes cancer." (PMID 29651002, 2018). "In both categories of women, there were obesity, elevated blood glucose levels with poor glycemic control, and deranged lipid metabolism, with the postmenopausal women presenting with significantly elevated total cholesterol (p = 0.044) and fasting insulin (<0.0001)." (PMID 29808168, 2018). "In addition to being fat derived, adiponectin has recently been described as a myokine that regulates insulin sensitivity, which may link to exercise‐related metabolic benefits in obesity." (PMID 29446245, 2018). "This demonstrates that neither approach to linear modeling is fully compliant with the complexity of the biological relationship between BMI and insulin as the second ANOVA model enriched the IS correlated gene list with genetic loci associated with obesity rather than insulin." (PMID 29986096, 2018). "Therefore, the current study was designed to investigate the effects of HIIT on blood and skeletal muscle markers related to IR, MAPKs, mitochondrial biogenesis and oxidative metabolism in physically inactive insulin resistant and non-insulin resistant individuals with obesity." (PMID 30429793, 2018). "Thus, elevated hepatic SOCS3 levels in obesity impair both insulin and IL-6 signaling, thereby inducing a vicious cycle that might ultimately lead to cancer." (PMID 30591653, 2018). "Thus, the hepatic insulin/Snail1 axis is impaired in obesity." (PMID 30013137, 2018). "Likewise, contradictory evidence was shown associating irisin plasma levels with cardiovascular and metabolic parameters such as glucose, insulin resistance, and cholesterol and other lipid and fatty acid plasma levels in healthy children, as well as in those with obesity and the metabolic syndrome." (PMID 30477139, 2018). "Additionally, as demonstrated by several studies, systemic Irs2 knockout mouse models showed obesity and reduced insulin sensitivity, leading to impaired glucose tolerance and T2D; these results underline the importance of IRS scaffold proteins in insulin signal transduction." (PMID 30469501, 2018). "Thus, based on the systemic inflammatory state associated to the obesity, the oocyte maturation is variably affected by the altered balance of driver hormones as SHBG with other soluble factors including insulin, glucose, lactate, triglycerides, and C reactive protein." (PMID 29523133, 2018). "However, whether RES treatment could inhibit macrophage infiltration and regulate insulin signaling in insulin-sensitive WAT in obesity is still unknown." (PMID 29967759, 2018). "Furthermore, a reduction in mitochondrial oxidative capacity is linked to the development of T2DM and obesity (see “Metabolic syndrome and T2DM”), whereas exercise-enhanced mitochondrial performance is related to a better metabolic flexibility and insulin sensitivity (see “Cancer”)." (PMID 29697773, 2018). "However, elevations in blood glucose are a late manifestation of a disease that is preceded by other well-established indicators of diminishing metabolic health including obesity with accompanying lipid abnormalities or hyperlipidemia (HL), elevated fasting insulin or hyperinsulinemia (HI), and IR." (PMID 30271382, 2018).